MLX (MAX dimerization protein MLX)
Description:
Transcription regulator. Forms a sequence-specific DNA-binding protein complex with MAD1, MAD4, MNT, WBSCR14 and MLXIP which recognizes the core sequence 5'-CACGTG-3'. The TCFL4-MAD1, TCFL4-MAD4, TCFL4-WBSCR14 complexes are transcriptional repressors. Plays a role in transcriptional activation of glycolytic target genes. Involved in glucose-responsive gene regulation.
Synonyms: bHLHd13; TCFL4; MAD7; MXD7; TF4
Tractability: Small molecule: a high-quality ligand is known; it belongs to a druggable protein family. PROTAC: ubiquitination databases record sites on it; its protein half-life has been measured; a small molecule that binds it is known.
Gene: Protein-coding gene on chromosome 17 (42,567,072 to 42,573,239, forward strand). Ensembl gene ENSG00000108788.
Subcellular location: Cytoplasm (Isoform Alpha); Cytoplasm (Isoform Beta); Nucleus (Isoform Gamma)
Subcellular location (Human Protein Atlas): Nucleoplasm; Cytosol; Nuclear membrane
Pathways (Reactome):
Metabolism: ChREBP activates metabolic gene expression
Gene Ontology:
Molecular function: DNA binding; DNA-binding transcription repressor activity, RNA polymerase II-specific; protein binding; protein heterodimerization activity; protein homodimerization activity; RNA polymerase II transcription regulatory region sequence-specific DNA binding; RNA polymerase II-specific DNA-binding transcription factor binding; sequence-specific double-stranded DNA binding; DNA-binding transcription factor activity; DNA-binding transcription factor activity, RNA polymerase II-specific; RNA polymerase II cis-regulatory region sequence-specific DNA binding; protein dimerization activity
Biological process: negative regulation of DNA-templated transcription; negative regulation of transcription by RNA polymerase II; positive regulation of transcription by RNA polymerase II; glucose homeostasis; regulation of DNA-templated transcription; regulation of transcription by RNA polymerase II
Cellular component: cytoplasm; cytosol; nucleoplasm; nucleus; chromatin; RNA polymerase II transcription regulator complex; RNA polymerase II transcription repressor complex
Genetic constraint (gnomAD): Loss-of-function variants: 15 observed, 33.29 expected, observed/expected ratio (o/e) 0.45, 90% interval 0.3 to 0.69. The upper end of that interval is the gene's LOEUF score, 0.69, which puts it in group 2 of 6, group 1 being the genes least tolerant of losing a copy. Missense variants: 285 observed, 315.02 expected, observed/expected ratio (o/e) 0.9, 90% interval 0.82 to 1. Synonymous variants: 115 observed, 118.56 expected, observed/expected ratio (o/e) 0.97, 90% interval 0.83 to 1.13.
Homologues: Orthologues: chimpanzee MLX (100% identical), macaque MLX (99% identical), pig MLX (99% identical), dog MLX (98% identical), mouse Mlx (98% identical), rabbit MLX (97% identical), guinea pig MLX (95% identical), rat Mlx (94% identical), tropical clawed frog mlx (71% identical), zebrafish mlx (57% identical), Drosophila melanogaster bigmax (45% identical). Paralogues in human: MLXIPL (36% identical), MLXIP (33% identical), TFAP4 (18% identical).
Diseases named in the same sentence as MLX in open-access papers:
MLX is named in the same sentence as 33 diseases in open-access papers, as found by Europe PMC text mining. Sharing a sentence is not in itself a finding about the gene and the disease. The quoted sentences say what the papers report.
neuroblastoma (4 papers, 2018 to 2024). Neuroblastoma (NB) is the most common solid, extracranial childhood tumor. "Our earlier work in MYCN amplified neuroblastomas following MondoA or MLX knockdown linked growth arrest and apoptosis with attenuated lipid biosynthesis that could be rescued by OA." (PMID 34669700, 2021). "Notable DSGs included PKM, which has already been shown to undergo hnRNPA1-dependent alternative splicing in neuroblastoma and MLX, encoding a MYCN transcriptional co-activator regulating glutamine metabolism genes in neuroblastoma." (PMID 39313128, 2024).
osteosarcoma (4 papers, 2021 to 2024). A usually aggressive malignant bone-forming mesenchymal neoplasm, predominantly affecting adolescents and young adults. "To understand the mechanism underlying the tumorigenic function of MLX in osteosarcoma, we performed transcriptome sequencing (mRNA-seq) of MLX-silenced 143B cells." (PMID 37460542, 2023). "Furthermore, ChIP-seq binding profiles of these two patients and three publicly available osteosarcoma patients showed that MLX-associated super-enhancer sites were enriched in active histone modification marks such as H3K27ac." (PMID 37460542, 2023). "In addition, we found that the expression level of MLX is significantly higher in osteosarcoma and is associated with a poor prognosis." (PMID 37460542, 2023). "The oncogenic role of MLX has been reported in osteosarcoma, where enhancer-driven MLX expression is upregulated, contributing to metabolic reprogramming." (PMID 39391717, 2024). "To verify the results in clinical samples, we conducted RT-qPCR of 72 pairs of osteosarcoma samples, and the results showed significantly higher expression of MLX in osteosarcoma compared with paired normal tissues." (PMID 37460542, 2023). "We measured the IC50 of sulfasalazine in two aggressive osteosarcoma cell lines expressing high levels of MLX, and found that sulfasalazine significantly suppressed the proliferation of both cell lines." (PMID 37460542, 2023). "In the present study, we identified MLX as a super-enhancer-driven gene and revealed its oncogenic role in osteosarcoma." (PMID 37460542, 2023). "Collectively, these data suggest that MLX promotes osteosarcoma cell growth, invasion, and sphere formation in vitro, and MLX knockdown significantly suppresses the growth and metastasis of osteosarcoma in vivo." (PMID 37460542, 2023). "Collectively, these findings indicate that upregulation of SE-driven MLX in osteosarcoma is correlated with poor prognosis." (PMID 37460542, 2023). "To confirm the upregulation of MLX, we examined the expression of MLX in osteosarcoma cell lines, and we found that MLX was highly expressed in osteosarcoma cell lines compared to BMSCs." (PMID 37460542, 2023). "MLX is highly expressed in patients with osteosarcoma and plays an important role in promoting cell proliferation and invasion in vitro and in vivo." (PMID 37460542, 2023). "In conclusion, our results suggest a novel mechanism whereby super-enhancer-driven MLX rewires cysteine metabolism in osteosarcoma cells through SLC7A11 to cope with oxidative stress, which holds promise for therapeutic development in osteosarcoma." (PMID 37460542, 2023). "To investigate the expression of MLX in osteosarcoma, we first compared transcriptome sequencing data from the public osteosarcoma database and we found that MLX expression was markedly higher in osteosarcoma tissues than in bone marrow mesenchymal stem cells (BMSCs)." (PMID 37460542, 2023). "The application of lipid peroxidation inhibitors (liproxstatin-1 and ferrostatin-1) and iron chelators (deferasirox and deferoxamine/DFO) successfully rescued MLX-silenced osteosarcoma cells, verifying that knockdown of MLX could result in ferroptosis." (PMID 37460542, 2023). "Considering that upregulation or amplification of MYC is a common event in osteosarcoma, the high demand for cystine might be at least partially met by MLX-mediated cystine uptake." (PMID 37460542, 2023). "Here, we sought to uncover the role of MLX, another member of the Myc-MLX network, in osteosarcoma." (PMID 37460542, 2023). "Knockdown of MLX impairs growth and metastasis of osteosarcoma in vivo and in vitro." (PMID 37460542, 2023). "Upregulation of MLX predicts a poor prognosis in osteosarcoma." (PMID 37460542, 2023). "Furthermore, using GSEA, we found that oxidative phosphorylation (OXPHOS) and ROS pathways were significantly enriched in the MLX knockdown group, suggesting that MLX can reprogram the metabolic pathways related to the redox balance in osteosarcoma cells." (PMID 37460542, 2023).
osteosarcoma (continued). "Additionally, we performed immunohistochemical staining for MLX on 62 paraffin sections of osteosarcoma tissues and evaluated their pathological scores." (PMID 37460542, 2023). "However, exactly how MYC influences the function of MLX in osteosarcoma remains unclear and needs to be explored." (PMID 37460542, 2023). "Mechanistically, MLX regulates the glutamate/cystine antiporter SLC7A11 to promote the uptake of extracellular cystine for biosynthesis of the essential antioxidant GSH, thereby maintain the redox balance in osteosarcoma cells." (PMID 37460542, 2023). "Mechanistically, MLX regulates the glutamate/cystine antiporter SLC7A11 to promote extracellular cysteine uptake required for the biosynthesis of the essential antioxidant GSH, thereby detoxifying reactive oxygen species (ROS) and maintaining the redox balance of osteosarcoma cells." (PMID 37460542, 2023). "Taken together, this study reveals a novel mechanism in which super-enhancer-driven MLX positively regulates SLC7A11 to meet the alleviated demand for cystine and maintain the redox balance, highlighting the feasibility and clinical promise of targeting SLC7A11 in osteosarcoma." (PMID 37460542, 2023).
Parkinson’s (2 papers, 2024). "Specific common coding variants in SPNS1 and MLX may be involved in Parkinson’s disease, and burden tests of rare variants further support that CNIP3, LSM7, NUCKS1 and the polyol/inositol phosphate biosynthetic pathway are associated with the disease." (PMID 37804111, 2024).
Takayasu arteritis (2 papers, 2020 to 2024). A rare inflammatory large-vessel vasculitis primarily affecting the aorta and its major branches, but also other large vessels, causing stenosis, occlusion, or aneurysm. "A recent genome-wide association study (GWAS) in Han Chinese population has revealed that several genes including MLX confer susceptibility to Takayasu arteritis (TA)." (PMID 33083483, 2020).
Aortic dissection (1 paper, 2022). Aortic dissection refers to a tear in the intimal layer of the aorta causing a separation between the intima and the medial layers of the aorta. "New genes (MLX, DAB2IP, EP300, ZFYVE9, PML, PRKCD) were suggested as candidate aortic dissection-associated genes, through correlation analyses performed on the results of a WES study on a cohort of 99 Chinese cases." (PMID 35892496, 2022).
germ cell tumor (1 paper, 2021). A benign or malignant, gonadal or extragonadal neoplasm that originates from germ cells. "Importantly, small interfering RNA (siRNA) against MLX resulted in similar changes in the male germ cell tumor (MGCT) cell line NTera2, supporting a cell autonomous role for MLX in regulating the expression of these SSC markers." (PMID 34669700, 2021). "These in vivo and in vitro studies implicate MLX and other members of the proximal MYC network, such as MNT, in regulation of metabolism and differentiation, as well as in suppression of intrinsic and extrinsic death signaling pathways in both spermatogenesis and male germ cell tumors (MGCTs)." (PMID 34669700, 2021).
glioma (1 paper, 2024). A benign or malignant brain and spinal cord tumor that arises from glial cells (astrocytes, oligodendrocytes, ependymal cells). "Some key factors that were previously overlooked have been revealed in our study, such as MLX, whose role in gliomas has never been addressed before." (PMID 39391717, 2024).
Hyperglycemia (1 paper, 2025). An increased concentration of glucose in the blood. "In cases of hyperglycemia, following G6P-promoted allosteric conformational changes, both MFPs translocate to the nucleus and independently bind the MLX transcription factor, activating the expression of genes via the ChoRE element within the promoters of target genes, such as TXNIP." (PMID 39851533, 2025).
Infertility (1 paper, 2021). "MLX targets Gapdhs, and loss of GAPDHS results in infertility and nonmotile spermatozoa." (PMID 34669700, 2021).
liver cancer (1 paper, 2015). An epithelial or non-epithelial malignant neoplasm that arises from the liver. "MLX plays a key role in glucose metabolism in pancreatic and liver tissues 38,39, and the overexpression of GLUT1 is involved in the pathogenesis of colon, pancreatic, and liver cancer." (PMID 25644309, 2015).
sterility (1 paper, 2021). "This suggests that critical MLX transcriptional targets in addition to TXNIP are responsible for the majority of the male-specific sterility phenotypes associated with loss of either MLX or MondoA." (PMID 34669700, 2021).
tumor (6 papers, 2021 to 2025). "In vitro and in vivo studies have shown that MLX plays an important role in tumor growth and metastasis." (PMID 37460542, 2023). "We previously demonstrated an obligate role for the MLX arm of the network in promoting survival of a wide range of tumor cells with deregulated MYC by facilitating metabolic reprogramming and suppressing apoptosis." (PMID 34669700, 2021). "Max-like protein X (MLX) was significantly activated in C1 tumor cell subsets." (PMID 39895784, 2025). "Here, we show that the glucose-sensing transcription factor (TF) MAX-Like protein X (MLX) and its binding partner MondoA are both required for male fertility in the mouse, as well as survival of human tumor cells derived from the male germ line." (PMID 34669700, 2021). "Furthermore, MLX also plays a pivotal role in MYC-induced tumorigenesis, underscoring the importance of MLX function in tumor development." (PMID 40073115, 2025). "Moreover, highly invasive cell lines with more aggressive tumor phenotypes, such as 143B and SJSA1, expressed higher levels of MLX." (PMID 37460542, 2023).
kidney (1 paper, 2022). "Many of these genes have been shown to be associated with steady-state, heat tolerance and renal function; for example, EXOC3 maintains organ homeostasis by driving lipid metabolism, FGR causes kidney injury, GPR3 is a receptor gene involved in adipose thermogenesis and MLX regulates metabolism." (PMID 36552284, 2022).
MLX also shares sentences with these, for which no sentence is quoted: cancer (3 papers); adenoma (1); Alzheimer disease (1); autoimmune disease (1); brain disorder (1); breast carcinoma (1); depression (1); diabetes (1); fluorosis (1); Insulin resistance (1); malabsorption syndrome (1); medullary thyroid carcinoma (1); melanoma (1); metabolic syndrome (1); myocardial infarction (1); nonalcoholic fatty liver disease (1); Obesity (1); T-cell leukemia (1); type 2 diabetes (1); Williams-Beuren syndrome (1).